DLGAP5 (DLG associated protein 5)
Diseases named in the same sentence as DLGAP5 in open-access papers (continued):
Sharing a sentence is not in itself a finding about the gene and the disease.
cancer (continued). "Fifth, the genes were previously associated with human cancers, in particular MAGEA12 however only DISCS LARGE (DROSOPHILA) HOMOLOG-ASSOCIATED PROTEIN 5 (DLGAP5) and MATRIX METALLOPEPTIDASE 1 (MMP1) have been previously reported to be up-regulated in HCC tumors." (PMID 23950870, 2013). "Besides, DLGAP5 is a potential cell cycle regulator in cancer cell carcinogenesis." (PMID 35873473, 2022). "Liu37 and others believed that DLGAP4 may have similar cancer-promoting functions as DLGAP5." (PMID 36396671, 2022). "Therefore, bL-mediated downregulation of CD44, ALDH1A1, and DLGAP5 could be an essential mechanism of inhibiting cancer cell proliferation, even though the suppression mechanism by bL is different." (PMID 30513573, 2018). "Therefore, DLGAP5 may likely contribute to hepatocarcinogenesis as a new cancer-testis (CT)-related gene that is involved in the de-differentiation of hepatocytes to an embryonic state." (PMID 24324629, 2013). "DLGAP5, also called DLG7, is a potential cell cycle regulator that may play a role in carcinogenesis, and it was identified in a gene co-expression analysis of multiple cancer datasets previously." (PMID 22956898, 2012). "Genes related to cancer stem cells and tumorigenesis, such as KPNA2, ECT2, ERCC6L and TUBB4B, and the cell-cycle regulators DLGAP5, KIF2C and BUB3 were also significantly upregulated in the CSPG+ group, and clustered well within the same area." (PMID 38251863, 2024). "This study found that in cancer types with over 12 tumor and para-cancer tissues, the genes RRM2, TK1, CCNB1, DLGAP5, CCNA2, MYBL2, and HJURP were repeatedly overexpressed across various cancer tissues." (PMID 39669580, 2024). "Due to their likely role in promoting cancer progression, ORC1L, KIF20A, DLGAP5, and RAB3B were selected as marker genes for downstream analysis." (PMID 37948380, 2023). "Multivariate Cox-proportional hazard model analysis was first conducted using hsa-mir-1247-3p, KIF20A, RAB3B, ORC1L, and DLGAP5 expression, MDSC, Th2, and HSC infiltration, LUAD cancer patient age and cancer stage as covariates to identify key markers promoting loss of patient survival rate." (PMID 37948380, 2023). "Although DLGAP5 has been studied in different tumors, respectively, there still remains lack of pan-cancer analysis that demonstrates the correlation between DLGAP5 and divergent tumor types." (PMID 34454476, 2021). "In recent years, there have been many studies on the relationship between DLGAP5 and different types of cancers, yet there is no pan-cancer analysis of DLGAP5." (PMID 34454476, 2021). "In the end, we identified six genes (DLGAP5, DSCC1, SSBP1, UBE2C, SNRPD1, and SMO) with a vital role in prevention of cell death in both cell lines and hence six potential drug targets for silencing in cancer therapy." (PMID 23251412, 2012).
tumor (49 papers, 2012 to 2026). "Moreover, univariate Cox regression analysis showed that TNM stage, clinical stage, tumor status, primary therapy outcome, and high expression of DLGAP5 were associated with poor OS (P < 0.05)." (PMID 38414025, 2024). "Interestingly, the DLGAP5-mutant group had a higher probability of tumor mutation burden (TMB), a quantifiable biomarker for immune checkpoint blockade (ICB) selection." (PMID 36712920, 2023). "In a mouse xenograft model, DLGAP5 knockdown significantly reduced 18F fluoro-D-deoxyglucose (18F-FDG) uptake which accurately reflects the level of glucose metabolism in tumor tissues and inhibited tumor growth." (PMID 39990228, 2025). "Immunohistochemical (IHC) staining revealed increased DLGAP5 expression in post-treatment tumor samples compared to pre-treatment samples, suggesting a critical role for DLGAP5 in GEM resistance of BLCA." (PMID 39990228, 2025). "CIBERSORT method and TIMER2.0 database was utilized to explore the relationship between DLGAP5 and tumor immune infiltration." (PMID 38414025, 2024). "In GBC cells, DLGAP5 promotes macrophage proliferation, migration, and M2 polarization, driving tumor progression." (PMID 39138521, 2024). "Then, given that DLGAP5 promoting tumor progression in LUAD, we also investigate the relationship of DLGAP5 with immune infiltration." (PMID 38414025, 2024). "While PBK, RRM2, and DLGAP5 contribute to tumor biology, their roles in genomic stability and mismatch repair are less direct, making them less immediate research priorities in this context." (PMID 39777332, 2024). "Overexpression of CCNB1, CCNB2, DLGAP5, and ASPM is associated with tumor progression and poor prognosis." (PMID 39045407, 2024). "DLGAP5 (also known as HURP or KI-AA0008) is a cell-cycle-regulated protein that plays a role in tumor development." (PMID 38144520, 2023). "In brief, DLGAP5 can affect patient prognosis or treatment outcome by reshaping the tumor microenvironment." (PMID 36712920, 2023). "Substantial stronger expression of DLGAP5 protein was found in LUAD tumor tissues compared with normal tissues through IHC staining from the HPA database." (PMID 36983664, 2023). "Subsequently, DLGAP5 expression, T stage, tumor status, and therapy outcome were collectively constructed as a nomogram." (PMID 36712920, 2023). "Immunohistochemistry (IHC) results from HPA demonstrated that DLGAP5 protein was found to be strongly expressed in BC tumor tissues, while SLC16A6, CAB39L, and HBA demonstrated lower protein expression in BC tissues." (PMID 37142271, 2023). "Several mitosis-associated genes, including AURKA, DLGAP5, TPX2, KIF11, and CKAP5, were overexpressed in tumor tissues, and associated with cell proliferation and poor OS." (PMID 36499051, 2022). "For those without normal tissue matched as controls in TIMER2 database, we utilized the GTEx dataset to further evaluate the disparity of DLGAP5 expression between normal and tumor tissues." (PMID 34454476, 2021). "DLGAP5 expression is regulated by the ubiquitin-proteasome pathway and participates in tumor cell migration and invasion." (PMID 34917126, 2021). "All of these provides solid basement and will promote more advanced understanding the role of DLGAP5 in tumorigenesis and development from the perspective of clinical tumor samples and cells." (PMID 34454476, 2021). "We analyze the genetic alteration status of DLGAP5 in TCGA cohorts, which included different subtypes of tumor samples." (PMID 34454476, 2021). "Among the five hub genes with prognostic values genes, four (CCNA2, DLGAP5, MAD2L1 and KIF2C) were associated with LUSC tumor grade." (PMID 32411535, 2020).
tumor (continued). "The growth rate of tumor tissues depends to some extent on the activity of mitosis, so the importance of DLGAP5 in tumor generation and development is undeniable." (PMID 33312770, 2020). "Due to the vigorous proliferation requirement of tumor cells, there is a compensatory elevation of DLGAP5 expression." (PMID 33312770, 2020). "Then, immunohistochemical data provided by HPA were used to identify the different protein expression levels of DLGAP5 in tumor tissues and normal tissues." (PMID 33312770, 2020). "Among the five hub genes, the altered CCNA2, DLGAP5, MAD2L1 and KIF2C were associated with tumor grade, and were significantly up-regulated in LUSC compared with other NSCLC, implicating crucial roles of them in LUSC progression." (PMID 32411535, 2020). "The role of MYC in regulating the immune microenvironment is also significant, and further research could explore the role of DLGAP5 in the tumor immune microenvironment 71-73." (PMID 39990228, 2025). "Moreover, high DLGAP5 was associated with the sensitivity of frequently-used anti-LUAD drugs, advanced tumor stage and poor prognosis." (PMID 38414025, 2024). "Collectively, these resulting data suggest that DLGAP5 is involved in the regulation of tumor immunity to promote tumor development and may serve as a promising biomarker for immune checkpoint blockade therapy in LUAD." (PMID 38414025, 2024). "Based on these, we wonder whether DLGAP5 associates with the vital ICB-relevant genes and involves in the regulation of tumor microenvironment." (PMID 38414025, 2024). "In view of the imbalance of Th1/Th2 contributing to LUAD development, DLGAP5 may regulate the ratio of Th1/Th2 to promote tumor growth in LUAD." (PMID 38414025, 2024). "Furthermore, DLGAP5 assumes a significant function in the regulation of tumor immunity and treatment outcome of immune checkpoint inhibitors." (PMID 38414025, 2024). "Furthermore, DLGAP5 exerts a significant function in the regulation of tumor immunity and treatment outcome of immune checkpoint inhibitors." (PMID 38414025, 2024). "However, tumor cells exploit the property that DLGAP5 can regulate the cell cycle to promote proliferation." (PMID 36712920, 2023). "The role of disc large-associated protein 5 (DLGAP5) in LUAD progression and tumor microenvironment (TME) remains unclear." (PMID 36712920, 2023). "Meanwhile, DLGAP5 expression was associated with TNM stages, tumor status, and therapy outcome." (PMID 36712920, 2023). "Moreover, another study has proposed that DLGAP5 is a direct target of Notch3 and acts as a tumor suppressor by modulating the cell cycle in the G2/M phase, thereby repressing tumorigenesis and cell proliferation." (PMID 37958803, 2023). "In the first place, we analyzed the expression level of DLGAP5 in various cells and tumor tissues." (PMID 34454476, 2021). "Additionally, the GEPIA2 tool were used to aggregate all tumor expression data of TCGA and label the top 100 genes most related to DLGAP5 expression." (PMID 34454476, 2021). "Additionally, we tried to figure out the association between DLGAP5 expression and TMB (Tumor mutational burden), MSI (Microsatellite instability), respectively, based on TCGA datasets including all tumors." (PMID 34454476, 2021). "Although there have been bunches of studies conducted on the effect of DLGAP5, suggesting it exert effects on tumor cell proliferation by regulating cell cycle, our analysis of HCC cell lines pointed put the specific mechanisms to strengthen the migration and invasion ability of HCC cells." (PMID 34454476, 2021). "‘Cell cycle’ was suggested to be enrolled in the effect of DLGAP5 on tumor pathogenesis." (PMID 34454476, 2021). "CCNA2, DLGAP5, MAD2L1, and KIF2C were significantly up-regulated compared to other subtypes, and associated with tumor stage in LUSC, suggesting that they might tightly be involved in progression and prognosis of LUSC." (PMID 32411535, 2020).
tumor (continued). "Interestingly, in our present study, we revealed another crucial aspect of the regulatory impact of DLGAP5 on tumor microenvironment, as evidenced by the positive correlations between DLGAP5 and the essential immune checkpoint blockade (ICB)-related genes in LUAD." (PMID 38414025, 2024). "We speculate that DLGAP5 may inhibit the malignant phenotype of tumor cells through this pathway." (PMID 32782440, 2020). "Collectively, these results suggested that DLGAP5 may facilitate the formation of an immunosuppressive microenvironment where tumor cells evade the surveillance of the immune system, creating appropriate conditions for tumor cell proliferation while remaining unresponsive to immunotherapy." (PMID 36712920, 2023). "These candidates included five upregulated genes—NUF2, KIF4A, KIF18B, NEK2, and DLGAP5—and one downregulated gene—LRRK2—in the tumor tissues of TCGA databases." (PMID 36499051, 2022). "Consistently, NUF2, KIF4A, KIF18B, DLGAP5, and NEK2 were highly overexpressed, whereas LRRK2 was significantly downregulated in the tumor tissues of all datasets." (PMID 36499051, 2022). "The results of immunohistochemistry showed that protein expression levels of AURKA, CCNB1, DLGAP5, and NCAPG were upregulated in tumor tissue compared with normal tissue." (PMID 36250027, 2022). "In depth studies had found that DLGAP5 was an essential and conserved cell cycle regulating gene, whose expression level was affected by the degree of promoter methylation, controlled by hypoxia-control, and could enhance the resistance of tumor cells to chemotherapy and radiotherapy." (PMID 33312770, 2020). "NEK2, DLGAP5 and ECT2 expression levels were significantly elevated in tumor tissues compared with normal lung tissues." (PMID 28808310, 2017). "Our previous study revealed that DLGAP5 is markedly expressed in BLCA and promotes tumor growth." (PMID 39990228, 2025). "Furthermore, in a mouse subcutaneous xenograft model, tumors formed from DLGAP5-silenced cells exhibited greater sensitivity to GEM, as evidenced by reduced tumor size, weight, growth rate, and lower Ki-67 levels compared to control groups." (PMID 39990228, 2025). "First, we focused on the molecular functions of the DLGAP5-MYC loop in tumor cells without considering the tumor microenvironment." (PMID 39990228, 2025). "Additionally, CSC markers ADM, DLGAP5, S100A9, and TNFRSF11B showed consistent overexpression at both RNA and protein levels in tumor samples, with significantly lower expression in normal tissues." (PMID 40243557, 2025). "In addition, we explored the relationship between TRP-related prognostic features and TME and revealed strong correlations between ANLN, DLGAP5, FAM83A, PTTG1, and RHOV with tumor immune infiltration, immune checkpoints, and substance metabolism pathways." (PMID 39144144, 2024). "Results depicted that UCEC cases with altered DLGAP had a better prognosis in OS and PFS compared to cases without DLGAP5 alteration, which indicates that DLGAP5 is related to the poorer prognosis of tumor cases." (PMID 34454476, 2021). "Secondly, we did not define the expression and function of DLGAP5 in other tumor cells and tissues apart from HCC." (PMID 34454476, 2021). "NEK2, DLGAP5 and ECT2 were found to be highly expressed in tumor samples." (PMID 28808310, 2017). "However, the up-regulation of DLGAP5 positively correlated (P<0.05) with the level of alpha-fetoprotein (AFP) (P=0.036), the presence of portal vein tumor thrombus (PVTT) (P=0.015) and postoperative recurrence (χ2=4.255, P=0.039)." (PMID 24324629, 2013). "To further investigate the possible mechanism by which elevated DLGAP5 expression promotes the malignant process of LUAD, we evaluated the relationship between DLGAP5 and immune cell infiltration since tumor microenvironment is closely related to tumor development." (PMID 38414025, 2024).
tumor (continued). "DLGAP5 expression is not gender-biased in these tumours (TCGA-LIHC, p = 0.52, n = 115 female, n = 239 male), suggesting that interaction networks and background might play a role in the gene’s functionality." (PMID 30341281, 2018).
DLGAP5 also shares sentences with these, for which no sentence is quoted: glioblastoma (3 papers); esophageal cancer (2); lung squamous cell carcinoma (2); pancreatic adenocarcinoma (2); transitional cell carcinoma (2); uveal melanoma (2); adenocarcinoma (1); breast invasive carcinoma (1); cervical squamous cell carcinoma (1); cholangiocarcinoma (1); colon adenocarcinoma (1); colorectal tumors (1); endocervical adenocarcinoma (1); head and neck cancer (1); head and neck squamous cell carcinoma (1); Huntington disease (1); injury (1); kidney cancer (1); liver cirrhosis (1); meningioma (1); mesothelioma (1); Obesity (1); oligodendroglioma (1); polycystic ovary syndrome (1); prostate adenocarcinoma (1); rectum adenocarcinoma (1); sarcoma (1); Skin Cutaneous Melanoma (1); stomach adenocarcinoma (1); testicular germ cell tumor (1).
A further 3 diseases each share a sentence with DLGAP5 in 1 paper.